LCN2 (lipocalin 2)
Diseases named in the same sentence as LCN2 in open-access papers (continued):
Sharing a sentence is not in itself a finding about the gene and the disease.
tumor (continued). "In other studies, plasma levels of LCN2/matrix metallopeptidase 9 complex, MMP2, TIMP1, TIMP2 and TIMP3 were correlated to tumor size, lymph node involvement, tumor differentiation and prediction of tumor stage and T status in patients affected with HNSCC." (PMID 31014274, 2019). "Preliminary in vitro tests showed that co-cultures of 4T1 tumor cells with RAW264.7 macrophages secreted higher amounts of both CHI3L1 and LCN2 than either 4T1 or RAW264.7 mono-cultures." (PMID 30111338, 2018). "The lower local and systemic levels of both biomarker proteins in RAW264.7 inoculated mice at 5 w p.i. further indicated the critical importance of crosstalk with tumor cells and anti-inflammatory signaling for the induction of CHI3L1 as well as LCN2." (PMID 30111338, 2018). "Presumably, the epigenetic changes during tumor development and progression prevent the inhibitory effects of GPRC5A overexpression on Cp, LCN2 and POSTN in NSCLC cells." (PMID 28088789, 2017). "The role of lipocalin-2/MMP-9 complex consists in prevention of MMP-9 degradation and thus in the strengthening of the role of MMP-9 as a factor involved in tumor progression." (PMID 29089666, 2017). "Enhanced tissue expression as well as circulating levels of LCN2 and MMP9, or their complex, have been observed in several tumor entities." (PMID 27461255, 2016). "In our study, LCN2 inhibited the proliferation and metastasis/invasion of CRC cells in vitro, as well as tumor growth and lung metastasis in vivo." (PMID 27912767, 2016). "In the current study, we investigated the role of LCN2 in human CCA, including the effect of LCN2 on CCA cell growth and metastatic potential in vitro, and in vivo xenografted tumor growth." (PMID 27782193, 2016). "In contrast, the overexpression of LCN2 in PANC1 cells significantly increases invasion, attachment and tumor growth." (PMID 25476483, 2015). "In contrast, LCN2 overexpression in PANC1, with low endogenous expression, significantly increased invasion, attachment, and enhanced tumor growth." (PMID 23056397, 2012). "Knocking-down LCN2 in both BxPC3 and HPAF-II cells significantly reduced tumor growth when compared to the NS xenografts (p<0.01)." (PMID 23056397, 2012). "The aim of our present study was to investigate LCN2 expression in endometrial tumors with respect to clinico-pathologic phenotype, angiogenesis, EMT markers, vascular invasion by tumor cells, inflammatory markers and patient survival." (PMID 22559235, 2012). "In summary, we provide evidence utilising several cell lines that LCN2 promotes tumorigenicity in PDAC by enhancing invasion, tumour growth, angiogenesis, and gemcitabine resistance." (PMID 23056397, 2012). "In contrast, LCN2 was exclusively downregulated in SC, while EFNA1 expression decreased with tumor dedifferentiation." (PMID 21333016, 2011). "In a study recently published, basal-like tumour cell lines were characterized by the concomitant hypermethylation of a six gene panel (CDH1, CEACAM6, CST6, ESR1, LCN2, SCNN1A)." (PMID 20338046, 2010). "Some proteins from this list have also been identified in tumor studies as clinical outcome predictors (NOV, CLU TNC, POSTN, IGFBP2, LCN2) or mediators of resistance to chemotherapy (CLU, FBLN1, THBS, STIP1, PTGES3, IGFBP4, ATOX1)." (PMID 19936259, 2009). "Integration of PBMC and tumor profiles identified STEAP4, EPC1, CLEC1B, and LCN2 as shared DEGs." (PMID 41909879, 2026). "In this context, LCN2 interacts with MMP-9, stabilizing it and effectively exerting higher gelatinolytic activity on the extracellular matrix, enhancing matrix degradation, tumor progression and metastasis in BC." (PMID 41303420, 2025). "LCN2 levels can be stimulated by increased Her2 (also known as ERBB2) activity and an increase in p38 (also known as MAPK) activity, and both lead to increased invasion and tumor formation." (PMID 40356520, 2025).
tumor (continued). "LCN2 binds to SLC22A17 receptors on fibroblasts, activating STAT3, which further enhances fibroblast proliferation and secretion of MMPs and IL-6, reinforcing tumor growth and inflammation." (PMID 40472740, 2025). "Additionally, urinary LCN2 differentiated NMIBC and MIBC, as well as low‐ and high‐grade tumours from controls." (PMID 41363723, 2025). "Besides, the upregulation of LCN2 in TAM contributes to the enhancement of iron release from TAM to the TME, enhancing tumor growth." (PMID 40313933, 2025). "However, silencing LCN2 in tumor cells significantly attenuated these markers and reduced STAT3 phosphorylation in fibroblasts, indicating that LCN2 is a necessary paracrine effector downstream of EGFRvIII." (PMID 40472740, 2025). "STAT3 activated LCN2 secreted by neutrophils could also contribute to EMT, invasion and migration of tumour cells." (PMID 39021279, 2024). "High expression of LCN2 in neutrophil‐2 positively regulated the expression of VEGF to stimulate angiogenesis, and CEACAM6 induced neutrophil‐2 to adhere to the endothelial cells, further involving in angiogenesis and tumour progression." (PMID 39021279, 2024). "Furthermore, LCN2 is identified as a direct target gene of Hypermethylated in Cancer 1 (HIC1), a tumor suppressor specifically active in TNBC." (PMID 39188682, 2024). "Focusing on CRC patients with high tumor purity from the TCGA database, we found a resistant oncogenic signature of immune evasion (including REG4, CTSE, MUC1, TFF2, LCN2) that inversely correlated with cytotoxicity and immune infiltration deconvolution scores (T- and NK-cells)." (PMID 39632825, 2024). "Consistent with the results of TGCA analysis, LCN2 mRNA expression was upregulated in GC tissues compared to that in non-tumor tissues (p < 0.001), and a significant negative correlation was observed between LCN2 mRNA expression and GC grade." (PMID 39424639, 2024). "Targeting Lcn2 is similarly not straightforward because of the multitude of cellular sources (neutrophils, adipocytes, hepatocytes, tumor cells) and receptors (Slc22a17, MC4R, megalin)." (PMID 37648285, 2023). "Here, we show the osteogenic and tumor‐suppressive roles of SERPINA3 and LCN2 in BPCa." (PMID 37408474, 2023). "In addition to their individual diverse functions, LCN2, MMP9 and LOXL2 are all secreted proteins and are involved in reshaping the ECM, contributing to the progression, invasion, and migration of tumours." (PMID 37753805, 2023). "In summary, the LCN2/LOXL2/MMP9 ternary complex promoted the migration and invasion of cancer cells and malignant tumour progression through multiple mechanisms and could be a potential therapeutic target." (PMID 37753805, 2023). "In an inflammatory environment lacking Lipocalin 2, Alistipes species grow rapidly and promote the development of inflammation and tumor formation." (PMID 37313408, 2023). "In addition, ALOX15B, LCN2, PRSS12, CD79B and ITSN2 showed tumor lesion-specific changes for all four patients." (PMID 37488117, 2023). "Indeed, mammosphere formation of tumor cells was significantly upregulated by the DOX− 2nd CM compared to DOX+ 2nd CM-treated cells, and recombinant LCN2 rescued mammosphere formation in DOX+ 2nd CM-treated cells." (PMID 37174093, 2023). "LCN2/NGAL prevents bacterial development by securing iron-containing siderophores, while NOS2 produces nitric oxide, a reactive free radical that is a biological moderator in antibacterial, neurotransmission, and anti-tumor effects." (PMID 37259466, 2023). "Accordingly, LCN2 was screened as a key differentially expressed protein (DEP); moreover, upregulated LCN2 in tumor-infiltrating T cells had an immunosuppressive function and could promote tumor development." (PMID 38072118, 2023).
tumor (continued). "This study provides an overview on the epigenetic regulation of LCN2, SLC22A17, and MMP9 in the major tumor types allowing the identification of novel DNA methylation biomarkers and potential epi-drug targets of TME involved in tumor progression and drug resistance." (PMID 36211450, 2022). "The analyses revealed that the LCN2 gene and its isoform ENST00000277480.6 showed a positive correlation only with protein cluster 2 comprising EPPK1 and ECADHERIN (tumor group 1) and SLC1A5 and GCN5L2 (tumor group 6)." (PMID 36211450, 2022). "A recent study using RNA sequencing and immunohistochemistry revealed an overexpression of C-type lectin domain family 3 member A (CLEC3A), matrix metallopeptidase 7 (MMP7) and lipocalin 2 (LCN2) in recurrent PanNETs compared to non-recurrent tumor." (PMID 36551599, 2022). "Finally, the correlation analysis between genes and isoforms of LCN2, SLC22A17, and MMP9 in both normal and tumor samples was performed to detect any interaction between the three genes, including the relative isoforms." (PMID 36211450, 2022). "The role in tumorigenesis of LCN2, SLC22A17, and MMP9 genes and their gene isoforms as key players of TME interaction was assessed by performing differential transcriptomic analysis of these targets between TCGA tumor samples and GTEx normal tissues." (PMID 36211450, 2022). "Moreover, the impact of expression and methylation status of LCN2, SLC22A17, and MMP9 on overall survival and progression free interval was tumor type–dependent." (PMID 36211450, 2022). "The correlation analysis performed on all TCGA tumor types highlighted a negative correlation between LCN2 and SLC22A17 expression." (PMID 36211450, 2022). "To address the role of LCN2 in the collaboration between STAT3 and NF-kB activated by IL-6, we analyzed the expression of the STAT3-mediated PI3K signaling pathway and NF-kB/STAT3 target genes related to survival, anti-apoptosis, and tumor progression." (PMID 35470375, 2022). "LCN2 (but not NUPR1) mRNA expression was upregulated in the PDAC tumor group compared to the normal group." (PMID 33510144, 2021). "Disruption of the LCN2 gene in MMTV‐PyMT mice was found to suppress primary tumor formation without affecting lung metastasis." (PMID 34342930, 2021). "In mice bearing PDX line #4, treatment with the LCN2-neutralizing antibody did not alter tumor growth either with or without sorafenib co-treatment." (PMID 34921145, 2021). "These macrophages produce inflammatory cytokines that stimulate LCN2 expression on tumor cells but do not generate LCN2 themselves." (PMID 34207653, 2021). "Lcn-2 not only serves as a bacteriostatic agent secreted from MΦ during infection but is also being produced and released from TAM within the TME, with profound pro-tumor characteristics." (PMID 33808732, 2021). "Similar to the tissue-specific measurements, nuclear magnetic resonance (NMR) body composition analysis of the lean compartment also demonstrates a nonsignificant improvement in lean mass of Lcn2-KO tumor-bearing mice." (PMID 33824339, 2021). "Although there was a significant increase in Ppar-γ of Lcn2-KO mice, controlling for baseline genotypic expression did not result in a significant reduction in tumor-bearing mice between genotypes." (PMID 33824339, 2021). "CSF samples from five patients with LM were analyzed using single-cell RNA sequencing, showing that tumor cells, but not macrophages, within the CSF express the iron-binding protein lipocalin-2 (LCN2) and its receptor SCL22A17." (PMID 34207653, 2021). "In order to verify whether SLC7A11, GCLM, and GLS are specifically induced by iron-loaded Lcn-2, we stimulated CAKI1 tumor cells with iron-free, apo-Lcn-2 (aLcn-2) and a mutant form (mLcn-2) deficient of its iron binding capacity compared to hLcn-2." (PMID 34069743, 2021). "While TAM-derived Lcn-2 was correlated with tumor onset and lung metastasis, TAM-expressed FPN did not associate with any tumor parameter." (PMID 33808732, 2021).
tumor (continued). "We found that several secreted mediators encoding genes notably, LCN2 and S100A8 overexpressed at the distant metastatic site spine (LCN2, 5-fold; S100A8, 6-fold) and bone (LCN2, 5-fold; S100A8, 3-fold) vs. primary tumors in the syngeneic implantation/tumor-resection metastasis mouse model." (PMID 34072157, 2021). "The expression of Lcn2 showed no changes between treated conditions and controls, nor in tumor cells nor in TAM." (PMID 31413815, 2019). "In either case, previous studies have not evaluated the role of LCN2 on the remodeling or reprogramming of the premetastatic niche toward a tumor-permissive state." (PMID 31105883, 2019). "DFO treatment for 72 h decreased ferritin expression in TAM and in the tumor stroma but did not alter Lcn2 expression." (PMID 31413815, 2019). "On the other hand, our data indicates that long-term exposure of PCa cells on CXCL1 and LCN2 also triggers EMT, which is a well-known speculated mechanism of tumor metastasis." (PMID 31500632, 2019). "Both loss-of-function and gain-of-function experiments revealed that LCN2 could decrease the sensitivity of cisplatin in OSCC cells and xenografted tumours." (PMID 31819048, 2019). "Of note, LCN2 also stimulates VEGF expression via HIF and thus tumor angiogenesis." (PMID 30534534, 2018). "Mechanically, Lcn2 stabilizes and binds to MMP-9, resulting in matrix degradation and tumor EMT." (PMID 30591630, 2018). "The possibility that Lcn-2 is also provided by tumor-infiltrating immune cells was not fully appreciated." (PMID 28979267, 2017). "Taking into account that the tumor-promoting TAM phenotype also releases MMP-9, and its coformation with LCN2 may be well suited to promote cancer progression." (PMID 28804221, 2017). "Consequently, siderophore shuttling from tumor cells to TAM would allow Lcn-2 iron loading and the reverse transport of iron-loaded Lcn-2." (PMID 28979267, 2017). "Together, our data therefore imply that TCF7L1 accelerates human SCC cell migration and tumor growth through induction of LCN2 but does not require LCN2 to stimulate neutrophil infiltration." (PMID 28467300, 2017). "Furthermore, an SRB assay revealed that the tumour-suppressive effect of the culture supernatant was reduced by ARN1 and LCN2 treatment." (PMID 27507542, 2016). "LCN2 functions to protect matrix metalloproteinase-9 (MMP-9) against degradation, which further enhances its enzymatic activity and facilitates angiogenesis and tumor growth." (PMID 25476483, 2015). "Although these are common cellular responses in hypoxic tumor cells, the expression levels of LCN2 in hypoxic tumors have not been measured in detail." (PMID 25467539, 2014). "Collectively, our data supported that LCN2, which was able to detect HIF-1α-positive tumor cells, may be a useful plasma marker for hypoxic tumors." (PMID 25467539, 2014). "Lipocalin-2 was highly expressed in tumors from wild-type mice, but the expression did not correlate with tumor size." (PMID 22737251, 2012). "In PANC1 cells, LCN2 expression enhanced tumor growth (p = 0.00035), but was not correlated with increased resistance as gemcitabine (p<0.00001)." (PMID 23056397, 2012). "Because Lcn2 is a gene found in non-neoplastic cells that has been shown to function in the regulation of tumor cell growth and progression it fulfills the canonical definition of a proto-oncogene." (PMID 21649922, 2011). "This is important as this is the first iron-independent function of LCN2 that has been reported and opens up the possibility that there are other LCN2 functions required for tumor formation that are independent of the ability of LCN2 to regulate iron homeostasis." (PMID 40356520, 2025). "LCN2 expression did not influence tumor growth in either model." (PMID 41436606, 2025). "However, LCN2 did not impact tumor growth or angiogenesis in subcutaneous or orthotopic lung tumor models, highlighting its specific role within the brain metastatic niche." (PMID 41436606, 2025).
tumor (continued). "Multiple putative LCN2 receptors add further complexity, raising the possibility of receptor-specific targeting if subtype-specific expression patterns can be identified; however, it is not known which receptor contributes to LCN2-mediated tumor progression, invasion, or metastasis." (PMID 41303420, 2025). "LCN2 is a secreted siderophore-binding protein that can capture iron-containing complexes in iron-poor niches and deliver iron to cancer cells via specific receptors (e.g., SLC22A17/24p3R), thereby supporting tumor cell survival and proliferation under limiting-iron conditions." (PMID 41190142, 2025). "Additionally, LCN2 binds to its receptor SLC22A17 on tumor cells, activating the JAK2–STAT3 signaling pathway, which elevates VEGF-A expression and secretion, thereby promoting tumor neovascularization." (PMID 41436606, 2025). "Finally, our study has focused solely on one phenotype of LCN2 in CRC—metastasis, while other tumor-progression-influencing phenotypes such as proliferation and apoptosis still require in-depth investigation to explore LCN2’s broader potential and clinical significance." (PMID 40313933, 2025). "Additionally, LCN2 manipulation did not alter tumor cell transmigration across the blood‒brain barrier (BBB) in an in vitro BBB model, nor did it disrupt brain endothelial cell adhesion." (PMID 41436606, 2025). "Therefore, the LYZ, LCN2, CEACAM5, and AGRN genes, with specific expression along the malignant continuum, may serve as markers for CRC precancerous diagnosis and tumor progression detection." (PMID 39456726, 2024). "Although the role of these preclinical models in LCN2-mediated brain metastasis has not yet been clearly studied, they suggest that in various tumors, different cells within the microenvironment regulate LCN2 expression to promote tumor progression." (PMID 39188682, 2024). "In some studies, the expression level of Proteasome Subunit beta 8 (PSMB8), Lipocalin 2 (LCN2), T Cell Immunoreceptor with Ig and ITIM Domains (TIGIT), High Mobility Group Box (HMGBs) proteins, and others were found to be greater in tumor tissue as compared to normal tissue." (PMID 38730579, 2024). "However, splenocytes from mice vaccinated with VSV-IFNß-Lcn2 generated a Th1-like, IFN-γ response to these tumor targets which was significantly greater than that generated by VSV-IFNß alone, suggesting that this TAA may be a potential HCCTAA in this system." (PMID 38045348, 2023). "Finally, we discovered that the 12 IMRGs expression had significant differences, among which SFXN3, TFR2, TMPRSS6, HMOX1, and LCN2 expressions were elevated in the cancer group, and SCARA5, LTF, STEAP2, SLC39A14, CP, ALAS2, and TF were low expressed in the tumor group." (PMID 37361050, 2023). "Although there is already discussion whether LCN2 can be used as a reliable biomarker, there is still a lack of understanding on its exact function in tumor progression, especially in PCa." (PMID 35053376, 2022). "To study the role of LCN2 in NPC progression, we analyzed the dataset (GSE12452) from the Gene Expression Omnibus (GEO) database and found that the expression levels of LCN2 were significantly decreased in the tumor group (n = 31) compared with the normal group (n = 10)." (PMID 36428800, 2022). "At the molecular level, Lcn-2 is regulated through the activation of the signal transducer and activator of transcription 3 (STAT3) and CCAAT-enhancer-binding protein (C/EBP) β transcription factors in MΦ in response to the uptake and recycling of apoptotic tumor cells." (PMID 33808732, 2021). "In summary, our studies provide evidence, for the first time, that LCN2 is highly upregulated in IBC tumors and that it is required for tumor growth and skin invasion in mouse models of IBC; our findings further suggest that LCN2 could be a therapeutic target for IBC and other aggressive cancers." (PMID 34342930, 2021).